CD4 (CD4 molecule)
Diseases named in the same sentence as CD4 in open-access papers (continued):
Sharing a sentence is not in itself a finding about the gene and the disease.
infection (continued). "In this model, primary CD4 T cells from seronegative donors are activated via their TCR, then infected with a GFP-expressing reporter strain of HIV-1 (HIV-GFP) followed by enrichment of infected cells at 3 days post infection." (PMID 40198713, 2025). "Given that the cytokine responsiveness could be detected in both murine and human CD4 T cells and the diverse disease settings from which murine CD4 TIA cells can originate, we sought to determine when during the infection they first appear." (PMID 40923840, 2025). "Our study found that older age predicted higher viral loads and lower CD4 counts but did not independently predict infection stage, suggesting that behavioral factors mediate the effect of age on diagnosis timing." (PMID 41229481, 2025). "Throughout, the effect was even more dramatic for the primary strains, as evident by the fold increase in infection rates when HIV-1-infected macrophages were cocultured with autologous non-infected CD4+ T cells." (PMID 40130873, 2025). "A second relevant event is the selective and profound depletion of CCR5+ CD4 T cells in the GALT, which will remain severely and irreversibly damaged during the course of infection compromising the impermeability of the gastric epithelium and favouring bacterial translocation to the bloodstream." (PMID 41373539, 2025). "Effector CD4+ T cells in the brains of the SFV‐only and SFV + IAV–coinfected groups displayed similar activation phenotype of CD38+ PD1+, KLRG1+ compared with IAV‐only infection." (PMID 39971320, 2025). "The combination of CD4+/CD8+ T helper cells and vaccine/infection‐induced binding and neutralizing antibodies has been postulated as the main contributors of protection against infection." (PMID 40767533, 2025). "Nonetheless, we could show a KSHV-dependent accumulation of CD4+ LANA-specific, activated and early differentiated effector memory T cells at infection sites during KSHV infection of B cells in vivo." (PMID 41350288, 2025). "Although infection induced CD80, CD83, CD86, and HLA class II expression on the surface of DCs, the activation of CD4+ T cells was impaired, which is consistent with findings in RSV-infected murine DCs, where the formation of immunological synapses was impaired." (PMID 41280933, 2025). "To confirm the Luminex assay results that depletion of CD4+ T cells altered the relative levels of DENV2 TS and flavivirus CR Abs, we measured anti-NS1 ZIKV IgG levels with a different assay and at different timepoints after infection." (PMID 41295476, 2025). "As expected, comparison of T cells from naive versus LCMV-infected mice revealed the emergence of proliferating T cell clusters marked by Ki67 expression with infection, as well as that of exhausted CD8+ T cells and T helper 1 (TH1)-like CD4+ T cells, marked by high expression of Tox and Pdcd1." (PMID 41094201, 2025). "Among these, two were diagnosed with XLA and after infection did not mount detectable IgG response but exhibited CD4 T-cell responses (39-fold and 12-fold activation)." (PMID 41280926, 2025). "While CCR2ΔMHCII mice contained slightly fewer 2W:I-Ab-specific CD4+ T cells in the lungs than CCR2WT mice at 3 weeks post-infection, this difference was no longer observed by 6 weeks post-infection." (PMID 40489538, 2025). "When the piglets were pretreated with levamisole or 25–100 mg/kg baicalin, the CD3, CD4, CD8, and TIM3 mRNA levels were increased, in contrast with the infection group (p < 0.05), suggesting that levamisole and baicalin could modify T cell differentiation." (PMID 40427533, 2025). "The number of CD4+ T cells in the peritoneal cavity did not change appreciably in response to infection (except for a significant increase in the presence of CD154 blocking antibody that was due to two individuals with unusually high CD4+ T cell numbers)." (PMID 41388224, 2025).
infection (continued). "In addition, systemic T-cell activation in response to the infection is indicated by upregulation of the CD69 activation marker on CD8 and CD4 T-cells in the control animals." (PMID 41390777, 2025). "By comparison, no statistical differences in the frequency of EM CD4+T cells were observed among EBV status infection and between EBV-infected vs. NI children (KW and t-tests, respectively)." (PMID 40963636, 2025). "However, when groups were stratified by infection history, DENV-specific CD4+ and CD8+ T cell responses exhibited a higher magnitude after 2 infections only in children with subsequent inapparent infections." (PMID 39989460, 2025). "For instance, the HIV-1 T/F strain CH077 infected ~20% of macrophages at 50 ng of p24 inoculum when CD4+ T cells were added compared to nearly no infection without the addition of CD4+ T cells." (PMID 40130873, 2025). "Mice lacking CD4+ T cells exhibit higher MuGHV4 infection rates and persistence in AlvMφ, demonstrating a critical role of CD4+ T cell in controlling myeloid cell infection." (PMID 39796262, 2025). "By maintaining the expression of CD25, the virus ensures a productive infection, however in HIV infection where is perpetuated a repeated stimulation of CD4+ T-cells, also is favored an activation induced cell death (AICD) result of the co-expression of Fas and FasL." (PMID 40452022, 2025). "However, frequencies of naïve CD4 and CD8 T cells pre-transplant did trend lower in those who experienced post-transplant infection." (PMID 40475763, 2025). "Dysregulated immunity in CD4+, CD8+, and Treg subsets often persists for the first 3 months, with a partial functional shift becoming apparent between 3–6 months, the extent of which varies with initial infection severity." (PMID 41262872, 2025). "Reports have shown that vaccination could induce a robust CD4+ and CD8+ T cell response, and interestingly it has been reported one vaccination dose provided enhanced T cell responses in case of previous infection." (PMID 40431250, 2025). "We noticed a similar phenotype in the NHP model, in which we observed a major increase of activated CD4+ and CD8+ T cells in the blood within the first week after infection, although levels of LASV-specific IgG antibody responses were low to undetectable in terminally ill animals." (PMID 40996813, 2025). "In contrast, children with 2 or more prior DENV infections showed significantly higher DENV-specific CD4+ and CD8+ T cell frequencies associated with inapparent rather than symptomatic outcomes in subsequent infection." (PMID 39989460, 2025). "Because most infected cells harboring provirus are eliminated and only a subset of memory resting CD4 + T cells survive to persist during ART24,37, we hypothesized the size of infected cell clones might be stable throughout early infection and ART suppression." (PMID 39952916, 2025). "In an experimental infection of horses using virus mutants with multiple deletions, including ORF1 and ORF71, it was reported that CD8+ and INFγ-positive cells were dominant, whereas CD4+ and IFNγ-positive cells remained lower throughout the study." (PMID 39852824, 2025). "P. timonensis‐enhanced uptake increased productive infection in CD4+ T cells, but did not increase infection in moDCs or CD1c+ DCs." (PMID 40071689, 2025). "In parallel, we used intracellular cytokine staining to determine the frequency of R. rickettsii-specific IFN-γ-producing CD4+ T and CD8+ T cells in circulation on days 0, 50, and 57 post-primary vaccinations (note: day 57 is also day 7 post-infection challenge)." (PMID 41159782, 2025). "All utilized bnAbs reduced CD4+ T cell infection within the coculture of the lab-adapted strain HIV-1 NL4-3, with 3BNC117 and 10-1074 achieving complete neutralization, while PG9 only partially impaired the transmission of HIV-1 to CD4+ T cells." (PMID 40130873, 2025).
infection (continued). "When we previously examined homotypic T‐cell responses following COVID‐19 in SOT recipients (E.g., ancestral responses following ancestral infection or BA.1 responses following BA.1 infection), we observed a hierarchy: IL‐2 monofunctional > polyfunctional > IFN‐γ monofunctional CD4+ subsets." (PMID 40605422, 2025). "When considering the entire cohort, we did not identify discernible differences in the levels of overall DENV-specific CD4+ and CD8+ T cell responses between children who subsequently developed symptomatic infections and those who developed inapparent infections." (PMID 39989460, 2025). "Blocking both integrins significantly reduced CD4+ and CD8+ T cell recruitment to the brain at day 7 after infection, resulting in higher infectious burdens compared with isotype-treated mice concomitant with increased G-MDSC and PMN influx, resembling phenotypes in Rag1–/– animals." (PMID 39989461, 2025). "Interestingly, CD4+ T cells also display direct cytotoxicity akin to CD8+ T cells, killing infected cells and producing inflammatory cytokines to control the infection." (PMID 40431664, 2025). "While we observed a delay in emergence of T-cell activation in the CNS compartment compared to during untreated PHI, overall we found a higher frequency of CD8+ T cell activation in the CSF, and increasing frequencies of CD4+ and CD8+ T cell activation in the CSF during early infection prior to ART." (PMID 40070827, 2025). "Together, these results suggest that the increase in PLIN3 mRNA levels observed upon infection of primary CD4+ T cells is not due to increased stability of the transcript." (PMID 41085277, 2025). "We observed IL-22 induction from CD4+ T cell responses to both spike and non-spike antigens in children and to spike antigens in adults during the acute phase of infection." (PMID 40906527, 2025). "Infection significantly increased both CD4+ and CD8+ T cells in SCFM2-Scnn1b-Tg but not SCFM2-C57BL/6 mice." (PMID 40512037, 2025). "On the other hand, the ability to induce secondary CD8+ T cell responses without CD4+ T cell help has not been demonstrated in any models of infection or immunization." (PMID 39604225, 2025). "On the other hand, the response observed in our study is also dependent on the adaptive immunity, as Ciita—/— mice, lacking CD4+ T cells, are less protected against secondary infection." (PMID 40558085, 2025). "Consistent with monocyte infiltration into infected fLX being a dominant feature of our infection resolution model, systemic depletion of CD4 + cells, but not CD3 + cells, abrogated viral clearance." (PMID 40920821, 2025). "Exhaustion is not confined to CD8 T-cell responses; CD4 T-cells have also demonstrated functional unresponsiveness in the aftermath of various infections." (PMID 40868058, 2025). "Although CD4+, CD8+, and γδ T cells demonstrated comparable activation and differentiation kinetics in both groups, carriers showed pronounced reductions in IFN‐γ‐expressing CD4+ and CD8+ T‐cell frequencies during early infection." (PMID 41473407, 2025). "By day 17 post-infection, the CD19+ B cell population, along with the assayed markers, including CD38, PD-L1, Ki-67, and IRF4 within this population, was significantly higher in PBMCs depleted of CD4+ T cells compared with intact PBMCs." (PMID 40733503, 2025). "HuT 78 cells and primary CD4+ T lymphocytes from healthy donors were infected with equal p24 equivalents of the WT or ASP Mut12 viral stocks, and the extracellular level of p24 in culture supernatants were then quantified 24 h after infection." (PMID 41157603, 2025). "In cattle, although detailed mechanistic studies remain limited, emerging evidence supports the presence of robust T cell responses to both IAV and IDV, with virus-specific CD4+ and CD8+ T cells detected in respiratory and mammary tissues following infection or vaccination." (PMID 40872830, 2025).
infection (continued). "Similarly, it has been reported that CD4 and CD8 mRNA significantly up-regulated during tuberculin injection and the infection of Edwardsiella tarda and viral hemorrhagic septicemia virus in flounder (Paralichthys olivaceus)." (PMID 39944702, 2025). "However, strong accumulating evidence now supports the important and likely principal role that infected T cells, especially CD4+ memory T cells, play in HIV neuroinvasion, through entry into the brain and probably choroid plexus during early infection." (PMID 40110851, 2025). "IFN-γ is mainly produced by CD4 T cells early during infection, and a lack of IFN-γ results in extreme susceptibility, with mice succumbing to infection." (PMID 40937719, 2025). "CD4+ T-cells are essential for infection control and, seemingly, CD8+ cells do not contribute as much to the adaptive immune response." (PMID 41156789, 2025). "Analysis of the cell surface markers used for sorting revealed dramatic activation of CD4+ T cells in the first infection but not the second or third infections." (PMID 40214640, 2025). "We analyzed the ICs on CD4+ and CD8+ T cells at five longitudinal time points, revealing significantly lower frequencies of total ICs+ in CD4+ (0, 21, 49, and 133 days post-infection) and CD8+ T cells (0, 49, 84, and 133 days post-infection) in ECs across all phases." (PMID 40637373, 2025). "The FLAG‐CAR lentiviral vector successfully transduced activated T cells derived from human peripheral blood mononuclear cells (PBMC), achieving a robust transduction efficiency consistently exceeding 70% at a multiplicity of infection (MOI) of 2:1 and a balanced CD4:CD8 ratio." (PMID 40851786, 2025). "Included subjects were PLWH who initiated ART in the chronic stage of infection and had sustained virologic suppression (plasma HIV-1 RNA < 30 copies/mL) for a median of 9 years [IQR, 5–14], and who had a median CD4 T-cell count of 812 cells/μL [IQR, 590–956] at the time of sampling." (PMID 40920867, 2025). "Both CD4+ and CD8+ T cells were detectable following infection." (PMID 41345407, 2025). "Even in the absence of productive infection, activated immune cells stimulate bystander CD4+ T cells to undergo apoptosis by producing more TNF-α and IFN-γ." (PMID 41463453, 2025). "Importantly, the mouse model captures much of what is known about human immune responses to Mtb, including the importance of CD4 T cells and IFN-γ for immune control of infection." (PMID 40937719, 2025). "Both subsets are equally vulnerable to infection in vitro, although M-Mφ in vitro M. leprae-infected M-Mφ do not stimulate CD4+ T cells, despite stimulation with CD40 ligand and IFN-γ." (PMID 41306590, 2025). "In vitro, HIV enters CD4+ T cells but not myeloid cells exhibiting a permissive state, and pre-infection upregulation of VISORs is required for restriction." (PMID 39798087, 2025). "In parallel, we observed a pronounced increase in CD4+ effector memory T cells (TEM; CCR7−CD45RA−) relative to VACV-vaccinated individuals, consistent with the establishment of a robust effector memory compartment following natural infection." (PMID 41345407, 2025). "This damage could explain the significant decrease in naive CD4+ T cells observed in our cohort of PWH, consistent with previous report, even at an average of 9 months after mpox infection." (PMID 41204857, 2025). "Conversely, the effector CD4+ T‐cell population in IAV‐ and SFV + IAV–infected lungs displayed increased levels of both single‐positive and double‐positive CD38+ PD1+ phenotype cells compared with SFV infection at 7 and 10 dpi." (PMID 39971320, 2025). "Our acute infection studies in cell lines (THP-1 and SuP-T cells) and primary CD4 T cells indicated that the inhibition of RNAP III-mediated signaling may impact the establishment of latent reservoirs." (PMID 41012705, 2025).
infection (continued). "Next, to determine vaccine mediated ID93-stimulated CD4+ TH1 immune responses, splenocytes were isolated 4 wk post-third immunization and lung cells were isolated four weeks post-M.tb HN878 and M.tb H37Rv infection, and restimulated ex vivo with the ID93 fusion antigen." (PMID 40285479, 2025). "We find that PD-1 on CD4+ T cells operates extrinsically to limit expansion of brain antiviral CD8+ T cells and mitigate virus-induced neuroinflammation at the expense of checking infection." (PMID 41409145, 2025). "Since the Itgα4β7+ CD4+ T-cell subset predominantly consists of CCR6+ Th17 cells, their capacity to migrate into the GALT justifies our findings that CCR6+Itgβ7+ CD4+ T-cells are selectively targeted by HIV-1 for infection." (PMID 41227377, 2025). "We next investigated inflammasome activation in the context of cell-to-cell infection using primary CD4+ T cells as donor cells, rather than SUPT1 cells, and primary MDMs as target cells." (PMID 39229127, 2025). "Indeed, other studies have shown that viruses can downregulate their entry receptors post-infection (e.g., ACE2 and CD4 downregulation following severe acute respiratory syndrome coronavirus 2 and HIV infections, respectively)." (PMID 39846741, 2025). "At 4 weeks post-infection, T cell-deficient mice that received WT donor CD4+ T cells contained significantly more lung IFN-γ than mice that received IFN-γ-deficient CD4+ T cells or no CD4+ T cells." (PMID 40489538, 2025). "The limitation of this model was that the CD4+ T cells were stimulated to enhance infection with the R5-tropic, EGFP-reporter virus, and while the CD4+ T cells were rested for 48 hours, there may be persisting immune activation." (PMID 39902962, 2025). "Given the known limitations of non-targeted 10× 3′ PBMC assays and the absence of positives in uninfected controls, we report these findings descriptively and do not infer productive infection from RNA detected in non-CD4+ compartments." (PMID 41277843, 2025). "Similarly, naive CD4+ and CD8+ T cells (TN), which accounted for the majority of circulating T cells before infection, were also rapidly replaced by activated T cells at 4 DPI." (PMID 40996813, 2025). "While elevated CD57 expression has been previously reported in CD4+ T cells from ART‐treated, well‐controlled PWH, the significant increase observed in our PWH mpox+ cohort suggested heightened immune system pressure, likely due to previous MPXV infection." (PMID 41204857, 2025). "CD4+/CD8α- helper T cells did not vary significantly throughout infection, while CD4-/CD8α+ cytotoxic T lymphocytes (CTLs) decreased from 1 DPC to 5 DPC." (PMID 41156603, 2025). "In contrast, other HIV-related factors, such as duration of infection or CD4+ T lymphocyte counts at diagnosis or inclusion, were not identified as independent contributors to the atherosclerotic process." (PMID 40718411, 2025). "BMDC infection with M.tb CDC1551, measured TNF-α and IL-6 levels, and CD4+/CD8+ T cells in MLNS." (PMID 41256867, 2025). "Interestingly, at this early stage, LCMV-specific CD4+ T cells were already capable of producing IFN-γ upon antigen re-stimulation, indicating their functional maturity just three days post-infection." (PMID 40169810, 2025). "In fact, CD4 and CD8 T-cells play an essential role in eradicating MPXV, with an engagement of MPXV-specific αβ T-cell response in vivo during the early stages of infection, contributing to clearing the virus from the host." (PMID 39817429, 2025). "Nongravid recipients of IAV-specific memory CD4+ T cells had reduced lung viral titers versus naive recipients 4 days after infection." (PMID 39744951, 2025). "No CD4+ T cells were observed in the lungs of α-CD4-treated mice at week 3 post-infection demonstrating that the antibody depletion was effective." (PMID 40489538, 2025).